SLC35G1 (solute carrier family 35 member G1)
Description:
Chloride-sensitive citrate transporter localized on the basolateral membrane of enterocytes that mediates efflux of citrate into the bloodstream. May also play a role in intracellular calcium sensing and homeostasis by acting as a negative regulator of plasma membrane calcium-transporting ATPases, thereby preventing calcium efflux from the cell.
Synonyms: C10orf60; POST; TMEM20; FLJ33990
Tractability: Antibody: UniProt places it where antibodies can reach, with high confidence; its Gene Ontology location is reachable by antibodies, with high confidence; UniProt predicts a signal peptide or a membrane-spanning region.
Gene: Protein-coding gene on chromosome 10 (93,893,937 to 93,956,062, forward strand). Ensembl gene ENSG00000176273.
Subcellular location: Basolateral cell membrane; Cell membrane; Endoplasmic reticulum membrane
Gene Ontology:
Molecular function: citrate transmembrane transporter activity; protein binding
Biological process: calcium ion export across plasma membrane; intestinal absorption; regulation of cytosolic calcium ion concentration; citrate transport
Cellular component: basolateral plasma membrane; endoplasmic reticulum membrane; plasma membrane; membrane
Genetic constraint (gnomAD): Loss-of-function variants: 10 observed, 16.47 expected, observed/expected ratio (o/e) 0.61, 90% interval 0.37 to 1.03. The upper end of that interval is the gene's LOEUF score, 1.03, which puts it in group 4 of 6, group 1 being the genes least tolerant of losing a copy. Missense variants: 433 observed, 454.25 expected, observed/expected ratio (o/e) 0.95, 90% interval 0.88 to 1.03. Synonymous variants: 185 observed, 172.52 expected, observed/expected ratio (o/e) 1.07, 90% interval 0.95 to 1.21.
Homologues: Orthologues: chimpanzee SLC35G1 (99% identical), macaque SLC35G1 (91% identical), rabbit SLC35G1 (83% identical), guinea pig SLC35G1 (81% identical), mouse Slc35g1 (79% identical), rat Slc35g1 (78% identical), pig SLC35G1 (75% identical), dog SLC35G1 (62% identical), tropical clawed frog slc35g1 (61% identical), zebrafish slc35g1 (54% identical), Drosophila melanogaster CG5281 (34% identical). Paralogues in human: SLC35G2 (21% identical), SLC35G4 (18% identical), SLC35G3 (17% identical), SLC35G6 (17% identical), SLC35G5 (16% identical).
Diseases named in the same sentence as SLC35G1 in open-access papers:
SLC35G1 is named in the same sentence as 2 diseases in open-access papers, as found by Europe PMC text mining. Sharing a sentence is not in itself a finding about the gene and the disease.
SLC35G1 shares sentences with these, for which no sentence is quoted: hypothyroidism (1 paper); infection (1).